NCR1 (natural cytotoxicity triggering receptor 1)
Diseases named in the same sentence as NCR1 in open-access papers (continued):
Sharing a sentence is not in itself a finding about the gene and the disease.
AIDS (5 papers, 2014 to 2017). A syndrome resulting from the acquired deficiency of cellular immunity caused by the human immunodeficiency virus (HIV). "Regarding the mechanism of NCR regulation, quantitative RT-PCR measured comparable NKp46/NCR1 levels in AIDS-RL and controls, suggesting an identical regulation at both transcriptional and post-transcriptional levels." (PMID 25908934, 2014).
colon carcinoma (5 papers, 2013 to 2024). "ILC1s expressed inhibitory receptors and underwent inhibitory functional conversion in late stage colon cancers while ILC1s in early-stage tumors expressed high levels of activating receptors (KLRD1, NCR1, KLRC2, KLRB1C) while late-stage colon cancers expressed inhibitory markers (KLRE1, KLRA7)." (PMID 36189323, 2022).
gastrointestinal stromal tumor (5 papers, 2014 to 2022). "TNFR2 can also induce BIRC3/cIAP2 transcripts dependent on TRAF1 and decrease the transcription and expression of NKp46/NCR1, leading to tumor deterioration in mice and adverse outcomes in patients with gastrointestinal stromal tumors." (PMID 35494080, 2022).
asthma (4 papers, 2013 to 2018). "To further understand the role of NK cells in allergic inflammation we studied the role of NCR1 in a model of experimental asthma, classified as type 1 hypersensitivity reaction, in mice." (PMID 27580126, 2016). "The function of NCR1 was studied in a model of experimental asthma, classified as a type 1 hypersensitivity reaction, in mice." (PMID 27580126, 2016). "However, Ncr1‐DTA mice, which are genetically engineered to lack all NK cells in the most specific way to date, still robustly developed all asthma symptoms upon acute or chronic house dust mite exposure." (PMID 29444897, 2018). "Temporary depletion of NK cells during separate phases of asthma development in Ncr1‐DTR mice also had no impact on the inflammatory phenotype." (PMID 29444897, 2018).
breast tumors (4 papers, 2015 to 2024). "Finally, lower levels of several pro-inflammatory cytokines (IL1B, IL10, IL12, IL6, IL8, TNF), NK cell metagenes (NCR1, XCL1), cytolytic enzymes (GZMA, GZMB, PRF) and type I IFN-induced genes were also observed in IL-1R8 high breast tumors." (PMID 28533483, 2017).
malaria (4 papers, 2019 to 2024). Malaria is a serious and sometimes fatal disease caused by a parasite that commonly infects a certain type of mosquito which feeds on humans. "Among eukaryotes with NCR1 proteins but lacking receptor-mediated sterol uptake, malaria parasites are unusual in their requirement for functional NCR1, thus making this protein an exciting new antimalarial target." (PMID 30888318, 2019).
non-small cell lung carcinoma (4 papers, 2013 to 2025). A group of at least three distinct histological types of lung cancer, including non-small cell squamous cell carcinoma, adenocarcinoma, and large cell carcinoma. "Furthermore, in non-small cell lung cancer (NSCLC), the expression of activating receptors NCR1/2/3 in NK cells are decreased in peripheral NK cells." (PMID 38075202, 2024).
periodontitis (4 papers, 2012 to 2024). An acute or chronic inflammatory process that affects the tissues that surround and support the teeth. "In the first model we induced experimental periodontitis by orally infecting the Ncr1+/+ and Ncr1gfp/gfp animals with periodontal pathogenic bacteria." (PMID 22457623, 2012). "Collectively, we show that NCR1 and NKp46 play a critical role in the pathogenesis of F. nucleatum-mediated periodontitis." (PMID 22457623, 2012). "Here, we investigate the role played by the NK killer receptor NKp46 (NCR1 in mice), in the pathogenesis of periodontitis." (PMID 22457623, 2012). "Thus, the present study provides the first evidence that NCR1 and NKp46 directly recognize a periodontal pathogen and that this interaction influences the outcome of F. nucleatum-mediated periodontitis." (PMID 22457623, 2012). "To investigate this, we induced experimental periodontitis in wild type C57BL/6 mice and in the NCR1 knockout mice (Ncr1gfp/gfp, C57BL/6 background) that were generated in our laboratory by replacing the Ncr1 gene with GFP." (PMID 22457623, 2012).
Sepsis (3 papers, 2012 to 2021). Sepsis is defined as life-threatening organ dysfunction caused by a dysregulated host response to infection. "Mice whose NK cells lacked IL-10 (NCR1-CreERT2+/2 Rosa26-tdTomato IL-10flox/flox) had elevated weight loss, increased mortality, and prolonged signs of illness after undergoing CLP20-induced sepsis." (PMID 35053151, 2021).
cutaneous melanoma (2 papers, 2015 to 2022). A primary melanoma arising from atypical melanocytes in the skin. "We next assessed the survival and expression of NK cell markers (NCR1 and NCR3) and CD8 T cell markers (CD8A and CD8B) in 448 patients with skin cutaneous melanoma reported in the TCGA database." (PMID 36458012, 2022).
cutaneous T-cell lymphoma (2 papers, 2012 to 2019). "Malignant CD4+ T lymphocytes from patients with Sézary syndrome, an aggressive cutaneous T-cell lymphoma, express NCR1 mRNA and protein at the cell surface where it appears to display a novel inhibitory function." (PMID 22212381, 2012).
glioma (2 papers, 2017 to 2021). A benign or malignant brain and spinal cord tumor that arises from glial cells (astrocytes, oligodendrocytes, ependymal cells). "To determine the expression pattern of the PD-1/PD-L1 pathway and NCR1 in gliomas, we examined the RNA-sequencing data of gliomas from the GlioVis data portal to visualize and analyze brain tumor expression datasets." (PMID 34576141, 2021).
liver cancer (2 papers, 2018 to 2019). An epithelial or non-epithelial malignant neoplasm that arises from the liver. "In this study, the increased expression levels of miR-544 was shown to be inversely associated with the decreased expression of RUNX3 and NCR1 in NK cells separated from patients with liver cancer, while miR-544 was downregulated in IL-2 activated-NK cells in vitro." (PMID 29636640, 2018). "MiR-544 was significantly upregulated (P < 0.05) while NCR1 (P < 0.05) and RUNX3 (P < 0.05) were markedly downregulated in NK cells of liver cancer patients compared with those of healthy population, hinting that miR-544 level was negatively associated with the expression of NCR1 and RUNX3." (PMID 29636640, 2018). "miR-544 promoted the immune escape of liver cancer cells by downregulating NCR1 via targeting RUNX3." (PMID 29636640, 2018). "Collectively, these results manifested that miR-544 promoted immune escape in liver cancer by downregulating NCR1 via targeting RUNX3." (PMID 29636640, 2018). "Therefore, miR-544-induced NCR1 silencing was a promising factor for the immune escape of liver cancer." (PMID 29636640, 2018). "MiR-544 was upregulated while NCR1 and RUNX3 was downregulated in NK cells of patients with liver cancer." (PMID 29636640, 2018). "Overall, our study indicated that miR-544 overexpression in activated NK cells negatively regulated NCR1 through directly targeting RUNX3, resulting in suppressive cytotoxicity against liver cancer cells." (PMID 29636640, 2018). "The relative mRNA expression levels of miR-544 and NCR1 as well as the expression of RUNX3 at protein levels were measured using qRT-PCR and western blotting in NK cells isolated from healthy volunteers and patients with liver cancer." (PMID 29636640, 2018).
Stroke (2 papers, 2023). Sudden impairment of blood flow to a part of the brain due to occlusion or rupture of an artery to the brain. "Of the ILC family, mainly NKp46+ (encoded by the Ncr1 gene) NK cells and ILC1s responded to the stroke lesion." (PMID 36631780, 2023).
Allergy (1 paper, 2016). An allergy is an immune response or reaction to substances that are usually not harmful. "The ligand for NCR1 in allergy is unknown and further studies need to explore the interaction of NCR1 and its ligand, and how it affects the course of inflammation occurring during allergic airway inflammation." (PMID 27580126, 2016).
astrocytoma (1 paper, 2012). "In order to further validate de novo expression of NCR1 in astrocytes, we used an in vitro staining of the human astrocytoma U251 cell line grown to model whether cell stress could be associated with expression of NCR1." (PMID 22212381, 2012). "In order to further validate de novo expression of NCR1 in astrocytes, we used in vitro analysis of human astrocytoma U251 cells, a well-characterised permanent astrocytoma cell lines derived from patients with malignant astrocytomas and previously used in MS studies." (PMID 22212381, 2012).
chronic obstructive pulmonary disease (1 paper, 2021). A chronic and progressive lung disorder characterized by the loss of elasticity of the bronchial tree and the air sacs, destruction of the air sacs wall, thickening of the bronchial wall, and mucous accumulation in the bronchial tree. "In the next step, both the PDE6 and NCR1 genes were detected in the Chronic Obstructive Pulmonary Disease (COPD)-related Gene Set using Harmonizome on the collection of ‘omics’ Big Data sets." (PMID 33166390, 2021).
clear cell renal cell carcinoma (1 paper, 2022). "For example, although a four-gene signature (composed of NCR1, PRF1, CX3CL1 and CX3CR1) was shown to accurately distinguish NK-high vs NK-low subgroups in clear cell renal cell carcinoma, these genes are ubiquitously expressed by many immune cell types." (PMID 36685584, 2022).
Cognitive impairment (1 paper, 2024). Abnormal cognition is characterized by deficits in thinking, reasoning, or remembering. "If the causal association between NCR1 and cognitive impairment in APOEε4 carriers can be established, this may represent a drug repurposing opportunity." (PMID 39482741, 2024).
dementia (1 paper, 2024). Loss of intellectual abilities interfering with an individual's social and occupational functions. "Heterogeneity in the magnitude of the protein-dementia associations was observed among APOEε4 carriers for one NCR1 (one of the top four candidate proteins), GDF15, CHI3L1, and TFF3, each of which showed significant associations with VaD and comparatively weaker associations with AD dementia." (PMID 39482741, 2024). "Although peripheral T cell infiltration into the CNS has been identified as a potential driver of AD, particularly tau progression, whether peripheral or central NK cell activity, or NCR1 signaling in particular, influences risk for dementia remains an area of ongoing investigation." (PMID 39482741, 2024).
Niemann Pick type C disease (1 paper, 2025). "This is demonstrated for varying glucose influx and for yeast cells lacking the sterol transporters Ncr1 and Npc2, a model for Niemann Pick type C disease in humans." (PMID 40603986, 2025).
pancreatic ductal adenocarcinoma (1 paper, 2022). An infiltrating adenocarcinoma that arises from the epithelial cells of the pancreas. "However, other proteins such as TWEAK (tumor necrosis factor ligand superfamily member 12), NCR1 (natural cytotoxicity triggering receptor) and IL-6, which were widely used in our signatures, were not included in the pancreatic ductal adenocarcinoma signature." (PMID 36699667, 2022).
pneumonia (1 paper, 2020). An acute, acute and chronic, or chronic inflammation focally or diffusely affecting the lung parenchyma, caused by an infection in one or both of the lungs (by bacteria, viruses, fungi, or mycoplasma.). "The NCR1 (natural cytotoxicity receptor 1) on pulmonary NK cells controls their activation and the IFN-γ release during the early stages of S. pneumoniae-induced pneumonia without mediating the pathogen recognition." (PMID 32849610, 2020).
pulmonary hypertension (1 paper, 2018). Increased pressure within the pulmonary circulation due to lung or heart disorder. "We report the development of spontaneous pulmonary hypertension (PH) in both the Nfil3−/− and Ncr1-Gfp models of NK cell insufficiency, as exemplified by increased right ventricular systolic pressure (RVSP) and muscularization of the pulmonary arteries." (PMID 30234375, 2018).
systemic candidiasis (1 paper, 2024). "Consistent with this, Cg clearance in the murine systemic candidiasis model is dependent upon the recognition of three adhesins including Epa1, by the natural cytotoxic receptor NCR1 on Natural Killer cells." (PMID 38743788, 2024).
tumor (488 papers, 2005 to 2026). "For example, tumor-derived lactate causes a downregulation of NCR1 (NKp46), therefore, inhibiting NK cell cytotoxicity." (PMID 40427186, 2025). "This is most likely the result of NCR1 deficiency, resulting in reduced survival in the B16 tumor model." (PMID 37520575, 2023). "Analysis of our previously published RNA-Seq dataset, which includes various cell types found in OC ascites and omental metastases, showed selective expression of KIR2DL1, KIR2DL4, and NCR1 in tumor-associated NK cells (TANK), and KLRK1 and NCR3 in both TANK and tumor-associated T cells (TAT)." (PMID 39563446, 2024). "In contrast, killer cell lectin like receptor K1 (KLRK1; also known as NKG2D), CD226 molecule (CD226; also known as DNAM-1) and natural cytotoxicity triggering receptor 1 (NCR1; also known as NKp46) can bind to ligands on the tumour surface and activate NK cells, causing them to release cytotoxins." (PMID 39070147, 2024). "Natural cytotoxicity receptor NKp46, encoded by the Ncr1 gene, is a natural killer (NK) cell–activating receptor that plays roles in regulating the NK cell’s clearance of virus and rejection of tumor." (PMID 29702643, 2018). "Thus, we concluded that the O-linked residues of Ncr1 have an important role in its tumor ligand recognition." (PMID 27462433, 2015). "Thus, we concluded that the novel O-linked glycosylations of Ncr1 are important for its recognition of—and activation by—tumor ligands." (PMID 27462433, 2015). "Ultimately, NCR-1 immunofluorescence staining of tumor tissues from mice indicated that butyrate triggered an infiltration of NK cells into the tumor tissues." (PMID 40576244, 2025). "We annotated these clusters with canonical cell-type markers and identified tumor cells expressing Epcam and Nkx2-1, B cells expressing Cd19, T cells expressing Cd3d, and NK cells expressing Ncr1." (PMID 39718828, 2024). "Apart from executing immune surveillance and elimination functions by tissue-resident NK cells, circulating NK cells can also prevent tumor metastasis by activating the NKp46/NCR1 signaling." (PMID 38008741, 2023). "Immunostaining of CD8, CD4, and NKp46/NCR1 (used to evaluate natural killer cells) was performed to assess immunity against the tumor." (PMID 36996146, 2023). "The natural cytotoxicity receptor (NCR1) lineage is involved with activating NK cell cytotoxicity in response to tumor and viral ligand expression." (PMID 36671668, 2023). "Later studies employed Ncr1-/- mice to show that NKp46 is involved in the prevention of tumor metastasis." (PMID 36372017, 2022). "NKp30 (Natural Cytotoxicity Receptor 1, NCR1) is a powerful cytotoxicity receptor expressed on natural killer (NK) cells which is involved in tumor cell killing and the regulation of antitumor immune responses." (PMID 33671836, 2021). "Results displayed that miR-544 overexpression in vivo promoted tumor growth, downregulated NCR1 and reduced RUNX3 expression." (PMID 29636640, 2018). "LNK cells transfected with miR-544 mimic significantly led to enlargement of tumor volumes (P < 0.05), the enhancement of miR-544 and decrease of NCR1 expression at mRNA levels (P < 0.05) and the reduction of NCR1 and RUNX3 protein expression (P < 0.05)." (PMID 29636640, 2018). "We also observed pro-tumor NK cell activities to 66cl4 tumors, which the use of a NCR1 blocking mAb suggest are NCR1 mediated." (PMID 28969075, 2017). "Pretreatment of tumor cells with bacterial heparinase suppressed the enhanced binding of NCR1-Ig to BPTF KD cells and reduced the enhanced cytolytic activity of NK cells to 66cl4 BPTF KD targets." (PMID 28969075, 2017). "Ncr1 overexpressing cells exhibited higher degranulation levels upon challenge with the different tumor cells, compared to the GFP− cells." (PMID 29026144, 2017). "We next used the NCR1 blocking mAb in tumor bearing mice and observed that BPTF KD tumor weights are rescued with NCR1 blocking." (PMID 28969075, 2017).